HMGB1 (high mobility group box 1)
Diseases named in the same sentence as HMGB1 in open-access papers (continued):
Sharing a sentence is not in itself a finding about the gene and the disease.
emphysema (4 papers, 2017 to 2025). "HMGB1 was a driver gene in the brown module, which was associated with COPD, lung function and emphysema." (PMID 28287180, 2017). "In addition, the use of MSC‐derived exosomes can also inhibit the release of DAMPs caused by CS exposure, such as S100A4 and S100A8, HMGB1, RAGE and AGE, and thus reduce lung inflammation in animal models of emphysema." (PMID 36301039, 2022). "Besides, the emphysema index in HRCT was also correlated with HMGB1 levels in the peripheral airways." (PMID 36301039, 2022).
endometritis (4 papers, 2022 to 2025). An acute or chronic, usually bacterial infectious process affecting the endometrium. "Evidence suggests that HMGB1 is implicated in the development of endometritis and that endometritis causes HMGB1 to be increased in uterine tissues, serum, and uterine secretions; when endometrial inflammation occurs, HMGB1 is inhibited, and HMGB1 is reversed." (PMID 35565576, 2022). "The Western blot results indicated that Cl-amidine decreased the expression of citrullinated Histone H3 (Cit-H3) and high-mobility group box 1 protein (HMGB1) protein in LPS-induced rat endometritis." (PMID 35565576, 2022). "All results showed that Cl-amidine effectively reduced the expression of Cit-H3 and HMGB1 proteins by inhibiting the formation of NETs, thereby attenuating the inflammatory response to LPS-induced endometritis in rats." (PMID 35565576, 2022). "In conclusion, our data demonstrate that PGD2 modulates the release of HMGB-1 and HABP-2 in E. coli-infected endometritis in dairy cows, exhibiting distinct roles at different times." (PMID 40874199, 2025).
fibromyalgia (4 papers, 2022 to 2025). A chronic disorder of unknown etiology characterized by pain, stiffness, and tenderness in the muscles of neck, shoulders, back, hips, arms, and legs. "Our results indicated that both HMGB1 and S100B were increased after fibromyalgia induction, and this was mitigated by EA (Tukey’s test, * p < 0.05, n = 6) but not by PD-L1 injection." (PMID 41008336, 2025). "HMGB1 and S100B expression was markedly increased in the lumbar SC of the fibromyalgia mice compared to that in the normal mice (Tukey’s test, * p < 0.05, n = 6)." (PMID 41008336, 2025). "In addition, there were increased HMGB1 and S100B immuno-positive signals in the SSCs of the fibromyalgia mice compared to those in the normal mice (Tukey’s test, * p < 0.05, n = 6)." (PMID 41008336, 2025). "Next, we determined whether HMGB1 and S100B were involved in this fibromyalgia model and the effects of EA or PD-L1." (PMID 41008336, 2025). "The present study aimed to investigate whether EA reduces fibromyalgia pain by inhibiting the HMGB1, S100B, and TRPV1 signalling pathways in the mouse brain." (PMID 35341159, 2022). "Further, levels of microglia/astrocytes and also HMGB1 and S100B were increased, whereas PD-1 was decreased, in the DRG, SC, thalamus, SSC, and CB5-7 of fibromyalgia mice." (PMID 41008336, 2025). "Finally, we showed that S100B and HMGB1 regulate TRPV1 and its signalling pathways and propose TRPV1 as a potential therapeutic target for fibromyalgia." (PMID 35341159, 2022).
fungal infection (4 papers, 2019 to 2023). "Toll-like receptors (TLR2, TLR4), pro-inflammatory cytokines [tumor necrosis factor, interleukin 6 (IL-6), IL-1, and interferons], nuclear factor κB signaling, and HMGB1 were among top upstream regulators of the targets in fungal infection." (PMID 31969817, 2019). "Pathway analysis revealed that HMGB1 signaling is among the top 4 pathways in fungal infection." (PMID 31969817, 2019). "Upon the fungal infection, F. occidentalis expressed immune responses by activating DSP1, an ortholog of vertebrate HMGB1 known to act as a damage signal in response to pathogen infection in insects." (PMID 35450074, 2022).
glomerulonephritis (4 papers, 2013 to 2024). A renal disorder characterized by damage in the glomeruli. "However, whether leakage of HMGB1 into urine due to renal damage contributes to lower serum HMGB1 levels in parallel with increased urinary levels of HMGB1 in active glomerulonephritis in AAV is still unknown." (PMID 24007972, 2013).
gout (4 papers, 2011 to 2022). A condition characterized by painful swelling of the joints, which is caused by deposition of urate crystals. "Additionally, localization of HMGB1 in association with extracellular DNA released from neutrophils was detected in the synovial cells of gout patients." (PMID 32731558, 2020). "To determine if the inflammatory environment of gout, specifically IL-1 cytokines, promotes caspase-11 expression, we treated macrophages with IL-1α, IL-1β, and HMGB1." (PMID 31803174, 2019). "It has been reported that the transcription levels of IL-1β, IL-18, caspase-1, and HMGB1 in PBMC of patients with active gout were significantly higher than those in non-active patients or healthy controls." (PMID 35250993, 2022). "HMGB1 has been identified in NETs from patients with pediatric SLE, in extracellular DNA structures released from the synovial cells of patients with gout, in arterial coronary thrombi and in conditioned media of PMNs after inducing NETosis." (PMID 32731558, 2020).
head and neck cancer (4 papers, 2019 to 2023). A primary or metastatic malignant neoplasm affecting the head and neck. "In HPV-positive patients with head and neck cancers, high expression of high mobility group protein B1 (HMGB1) and anti-inflammatory cytokines may indicate immune evasion and disease recurrence and be employed as prognostic biomarkers." (PMID 37631922, 2023). "Among signaling proteins with a potential functional role in OSCC, the High Mobility Group Box 1 (HMGB1) protein has stimulated scientific interest due to frequent upregulation, and implication in the progression of many types of head and neck cancer types." (PMID 37511951, 2023).
hemorrhagic fever (4 papers, 2015 to 2023). An infectious disease caused by certain viruses or bacteria that can damage the walls of tiny blood vessels, making them leak, and can hamper the blood's ability to clot and cause severe, life-threatening illness. "According to that, our results indicated that HMGB1 is likely to be involved in the immunopathogenesis of hemorrhagic fevers." (PMID 27348219, 2016). "Another proinflammatory marker connected to prognosis of hemorrhagic fevers is High Mobility Group Box 1 (HMGB1)." (PMID 27348219, 2016). "According to the observed kinetic, we have further evaluated the HMGB1 concentration in the first available serum sample of patients with hemorrhagic fever." (PMID 27348219, 2016). "One such study proposed HMGB1 as a potential biomarker of severe hemorrhagic fever infection." (PMID 34615921, 2021). "Because of immune-mediated response of HMGB1 further immunological studies are needed to clarify, whether HMGB1 can be used as a prognostic marker for hemorrhagic fever outcomes." (PMID 27348219, 2016). "To examine whether the demographic influenced concentration of HMGB1, we have analyzed the age and gender composition of patients with hemorrhagic fevers." (PMID 27348219, 2016). "To investigate whether HMGB1 concentration is elevated in patients with hemorrhagic fever, we compared HMGB1 levels between 72 patients with HFRS, 56 patients with CCHF and 61 healthy donors." (PMID 27348219, 2016). "Our results indicated that age and gender distribution have no influence on concentration of HMGB1 in patients with hemorrhagic fevers." (PMID 27348219, 2016).
hemorrhagic stroke (4 papers, 2012 to 2022). A stroke caused by a bleed on the brain. "TBI and ischemic and hemorrhagic stroke are all characterized by increased levels of intraparenchymal thrombin and HMGB1 as well as evidence of BBB dysfunction." (PMID 27553758, 2016). "Therefore, anti-HMGB1 has been demonstrated to have beneficial effects on both ischemic and hemorrhagic stroke." (PMID 36230933, 2022). "A great body of evidence suggests that the increased levels of HMGB1 in the CSF and in the systemic circulation, after ischemic and hemorrhagic strokes, are due to the release of HMGB1 from damaged cells that gains entry into these compartments through the disrupted BBB." (PMID 32295146, 2020).
hyperhomocysteinemia (4 papers, 2021 to 2025). A serious metabolic condition caused by mutations in the MTHFR gene, medications, or nutritional deficiency. "Silencing of HMGB1 has been shown to reduce pyroptosis caused by hyperhomocysteinemia." (PMID 41378869, 2025). "Hyperhomocysteinemia (HHcy) worsens cardiovascular outcomes by impairing vascular function and promoting chronic inflammation via release of danger-associated molecular patterns, such as high-mobility group box-1 (HMGB-1)." (PMID 37513606, 2023).
Hyperinsulinemia (4 papers, 2015 to 2025). An increased concentration of insulin in the blood. "In PCOS women, insulin sensitivity was assessed by the glucose clamp technique and HMGB1 was measured at baseline and after acute hyperinsulinemia." (PMID 37256493, 2023). "Interestingly, we observed increased serum HMGB1 levels during acute hyperinsulinemia (4.77 ± 3.16 ng/ml during hyperinsulinemia vs 4.11 ± 3.22 ng/ml at baseline, p = 0.028)." (PMID 37256493, 2023). "Interestingly, HMGB1 is involved with some typical IR/hyperinsulinemia-related disorders, such as type 2 diabetes and obesity, and its circulating concentrations have been reported to be higher in PCOS than in non-PCOS women, in a study carried out in subjects undergoing in vitro fertilization." (PMID 37256493, 2023). "In addition, serum HMGB1 was inversely associated with both total glucose disposal (M-clamp value) and non-oxidative glucose metabolism during hyperinsulinemia." (PMID 37256493, 2023). "Therefore, it is reasonable to speculate that the IR-induced hyperinsulinemia could contribute to modulate HMGB1 production." (PMID 26317615, 2015).
hypoxic-ischemic encephalopathy (4 papers, 2021 to 2022). "Clinical studies have demonstrated that HMGB1 levels are elevated in the blood of neonates with perinatal asphyxia and in the umbilical blood of neonates suffering from hypoxic-ischemic encephalopathy." (PMID 34867200, 2021).
inflammatory skin disease (4 papers, 2021 to 2023). Inflammatory skin disorders covers a broad category that includes many conditions ranging in severity, from mild itching to grave medical health complications These disorders are common in people of all ages and races. "Nevertheless, the contribution of HMGB1 secreted from keratinocytes to inflammatory skin diseases has not been well characterized." (PMID 36344541, 2022).
leukocytosis (4 papers, 2013 to 2024). "Moreover, leukocytosis correlated with higher HMGB1 secretion at diagnosis (a median WBC count of 8.6×109/l)." (PMID 28404891, 2017).
malignant pleural mesothelioma (4 papers, 2013 to 2024). A malignant neoplasm that arises from mesothelial cells in the pleura and shows a diffuse growth pattern. "Therefore, the PLF of rats with either developing or advanced malignant pleural mesothelioma would be expected to contain elevated levels of HMGB1, as is the case for the rats administered MWCNT-7." (PMID 35449069, 2022).
mastitis (4 papers, 2015 to 2025). Inflammation of breast tissue during lactation or postpartum due to an obstructed duct or infection. "Additionally, bta-miR-223 plays a role in the immune response to mastitis in dairy cows by targeting the HMGB1 gene." (PMID 40005551, 2025). "Additionally, our findings suggested that the anti‐inflammatory action of LYZ can be achieved by regulating HMGB1 expression, thereby mitigating the progression of mastitis." (PMID 39099401, 2024). "Nanocurcumin alleviates inflammation and oxidative stress in LPS-induced mastitis by activating Nrf2 and inhibiting TLR4-mediated NF-κB and HMGB1 signaling pathways." (PMID 41012726, 2025). "Therefore, LYZ can regulate the inflammatory response by down‐regulating the expression of HMGB1 in gene‐edited GMEC, which is one of the regulatory mechanisms of the anti‐mastitis in vivo following high LYZ expression in GED goats." (PMID 39099401, 2024). "Additionally, our study confirmed the involvement of PANoptosis in BMB damage during mastitis pathogenesis and shed light on the potential regulatory mechanism of LYZ's anti‐inflammatory effect through regulating high mobility group box 1 (HMGB1) expression." (PMID 39099401, 2024).
meningitis (4 papers, 2016 to 2025). A disorder characterized by acute inflammation of the meninges of the brain and/or spinal cord. "Of note, daptomycin co-application was capable of dampening the adverse (side) effect of anti-HMGB1 on the meningitis-associated increase in cerebral bleeding." (PMID 29096648, 2017). "Considering body temperature, anti-HMGB1 and paquinimod (mono) therapy were associated with milder meningitis-associated hypothermia than that found in positive control groups, while the combination of anti-HMGB1 and paquinimod showed body temperatures equal to these control groups." (PMID 29096648, 2017). "And previous reports of HMGB1 in human meningitis have been considered only for specimens with a relatively small sample size and at early time points of the disease." (PMID 39849347, 2025).
myeloid leukemia (4 papers, 2012 to 2025). A clonal proliferation of myeloid cells and their precursors in the bone marrow, peripheral blood, and spleen. "miR‐181b was found to inhibit high mobility group box 1 (HMGB1) and myeloid leukaemia (MCL‐1) while HMGB1 was expressed at high levels in relapsed/refractory AML patients." (PMID 36051053, 2022).
oral cancer (4 papers, 2014 to 2024). "However, accumulating research data revealed that the upregulation of HMGB1 in OSCC is involved in the development and pathology of oral cancer as well as in chemotherapy-associated oral mucositis." (PMID 37511951, 2023). "Drugs/molecules used in experimental studies to attenuate HMGB1 effects in oral cancer." (PMID 37511951, 2023). "Moreover, HMGB1 gene haplotypes (AGC and GGC) were shown to be correlated with elevated risk of oral cancer and oral lichen planus progression to OSCC." (PMID 37511951, 2023). "In oral cancer, HMGB1 has been reported to promote lymphangiogenesis through the upregulation of vascular endothelial growth factor C (VEGF-C) and vascular endothelial growth factor D (VEGF-D), which might be linked to the transmigration of HMGB1." (PMID 25622595, 2015). "Therefore, inhibiting HMGB1 and its downstream signaling pathways may be a mechanism-based antitumor approach for treating advanced oral cancer." (PMID 37897664, 2024). "Furthermore, the diverse single-nucleotide polymorphisms (SNPs) of HMGB1 are associated with OSCC, and the 1177GG genotype of HMGB1 is correlated with lymphatic metastasis and tumor stage in OSCC, suggesting that HMGB1 haplotypes may be relevant to the susceptibility to oral cancer." (PMID 37897664, 2024).
pleural mesothelioma (4 papers, 2019 to 2022). A neoplasm that arises from the mesothelial cells of the pleura. "High expression of HMGB1 was significantly associated with poor survival (median survival time = 9.6 months), while high expression of fibulin-3 and HMGB1 combination was associated with poor survival among patients of pleural mesothelioma (median survival time = 10.5 months)." (PMID 33230247, 2020). "Serum mesothelin has been identified as a biomarker for the detection of pleural mesothelioma but with limited results while other researchers have investigated the role of serum levels of High Mobility Group Box 1 protein (HMGB1), ostheopontin, proteomics-based approaches, fibulin-3 and microRNAs." (PMID 31207975, 2019).
pulpitis (4 papers, 2014 to 2025). Inflammation of the dental pulp. "Our results demonstrated that HMGB1 translocated from the nuclei to the cytoplasm and was then secreted out from pulpitis tissue." (PMID 25114379, 2014). "The expression of HMGB1 in the nuclear and cytoplasmic extracts of pulp tissue samples from 3 separate patients with pulpitis (patients 1–3) and 3 healthy control subjects (patients 4–6) was determined by western blot analysis." (PMID 25114379, 2014). "Strong cytoplasmic HMGB1 immunoreactivity was noted in odontoblasts, whereas nuclear HMGB1 immunoreactivity was seen in stromal pulp fibroblasts-like cells in human pulpitis tissue." (PMID 25114379, 2014). "Our findings demonstrated a distinct translocation of nuclear HMGB1 to the cytoplasm in tissues from the pulpitis patients, whereas HMGB1 was present only in the nuclei of healthy tissues." (PMID 25114379, 2014). "In pulpitis patients, HMGB1 levels are markedly elevated compared to healthy pulp tissue." (PMID 41142308, 2025). "HMGB1 inhibitors alleviate pulpitis by blocking its interaction with receptors such as RAGE and TLR4, leading to reduced pro-inflammatory cytokine production in a dose-dependent manner, as demonstrated by systemic intraperitoneal administration in animal studies." (PMID 41142308, 2025). "The present study has shown that RAGE and cytoplasmic HMGB1 are upregulated in pulpitis tissue." (PMID 25114379, 2014). "Furthermore, HMGB1 was solely localized in the nucleus of odontoblasts in healthy tissues, while a significant proportion of HMGB1 translocated to the cytoplasm in pulpitis tissue, which correlates with an increase in extracellular HMGB1 in LPS stimulated OLC-1 cells." (PMID 25114379, 2014). "The finding that HMGB1 acts as a proinflammatory mediator in pulpitis may provide new avenues for anti-inflammatory intervention, such as inhibiting the downregulation of dentin formation and production of proinflammatory molecules, thus suppressing dental pulp abscess formation." (PMID 25114379, 2014). "Therefore, secreted HMGB1 from odontoblasts may contribute to the progression of human pulpitis pathogenesis." (PMID 25114379, 2014). "It has also been demonstrated that high levels of cytokines in pulpitis such as IL-6, IL-1, and TNF-α are also released by HMGB1 secretion." (PMID 32760399, 2020). "Our data show for the first time that LPS from P. intermedia would be able to upregulate the danger signals HMGB1 and RAGE in human dental pulp inflammation." (PMID 25114379, 2014). "Our studies illustrate that HMGB1 release following P. intermedia LPS stimulation was suppressed by RAGE knockdown OLC-1, suggesting that overexpression of RAGE was essentially required for subsequent HMGB1 release, contributing to the progression of pulpitis." (PMID 25114379, 2014). "Therefore, understanding the mechanisms regulating the proinflammatory mediator HMGB1 and its receptor RAGE may lead to novel therapeutic approaches in pulpitis." (PMID 25114379, 2014). "In addition, our findings demonstrated only a distinct translocation of nuclear HMGB1 to the cytoplasm of odontoblasts but not pulp fibroblast-like cells in tissues from the pulpitis patients." (PMID 25114379, 2014). "The aim of this study was to examine whether RAGE and HMGB1 are involved in the pathogenesis of pulpitis and investigate the effect of Prevotella intermedia (P. intermedia) lipopolysaccharide (LPS) on RAGE and HMGB1 expression in odontoblast-like cells (OLC-1)." (PMID 25114379, 2014). "Thus, targeting necroptosis by inhibiting DAMPs like HMGB1 and pro-inflammatory cytokines such as TNF-α may reduce inflammatory mediators, disrupt the inflammatory cycle, and promote pulp tissue repair, offering a promising therapeutic strategy for pulpitis." (PMID 41142308, 2025).
renal carcinoma (4 papers, 2017 to 2024). A carcinoma arising from the epithelium of the renal parenchyma or the renal pelvis. "Furthermore, a recent study showed that the treatment of renal cancer cells with recombinant HMGB1 induced vimentin/α-SMA expression and phenotypic change." (PMID 28727734, 2017). "We also found that Cabozantinib treatment did not modulate HMGB1 release in renal cancer cell lines." (PMID 34745989, 2021). "In addition to HMGB1 we investigated the expression levels of VEGFA, as a main target in renal cancer treatment strategies." (PMID 30123419, 2018).